KRTAP5-3 (keratin associated protein 5-3)
Description:
In the hair cortex, hair keratin intermediate filaments are embedded in an interfilamentous matrix, consisting of hair keratin-associated protein (KRTAP), which are essential for the formation of a rigid and resistant hair shaft through their extensive disulfide bond cross-linking with abundant cysteine residues of hair keratins. The matrix proteins include the high-sulfur and high-glycine-tyrosine keratins.
Synonyms: KRTAP5-9; KRTAP5.3
Tractability: No criterion of Open Targets' tractability assessment is met for any kind of drug.
Gene: Protein-coding gene on chromosome 11 (1,607,565 to 1,608,463, reverse strand). Ensembl gene ENSG00000196224.
Pathways (Reactome):
Developmental Biology: Keratinization
Gene Ontology:
Molecular function: protein binding
Cellular component: cytosol
Genetic constraint (gnomAD): Loss-of-function variants: 1 observed, 2.74 expected, observed/expected ratio (o/e) 0.37, 90% interval 0.13 to 1.55. That is too few expected variants to judge how well the gene tolerates losing a copy. Missense variants: 229 observed, 285.34 expected, observed/expected ratio (o/e) 0.8, 90% interval 0.72 to 0.89. Synonymous variants: 92 observed, 112.92 expected, observed/expected ratio (o/e) 0.81, 90% interval 0.69 to 0.97.
Homologues: Paralogues in human: KRTAP5-4 (73% identical).
Diseases named in the same sentence as KRTAP5-3 in open-access papers:
KRTAP5-3 is named in the same sentence as 1 disease in open-access papers, as found by Europe PMC text mining. Sharing a sentence is not in itself a finding about the gene and the disease. The quoted sentences say what the papers report.
cancer (1 paper, 2024). A tumor composed of atypical neoplastic, often pleomorphic cells that invade other tissues. "Among them, Sialic acid-binding immunoglobulin-like lectins 10 and 11 (SIGLEC10, SIGLEC11) and Keratin-associated protein 5 (KRTAP5-3) transcripts, genes known to be involved in cancer progression, turned out to be up-regulated only in TPC-1-exo." (PMID 38338696, 2024).